USP10 (ubiquitin specific peptidase 10)
Diseases named in the same sentence as USP10 in open-access papers (continued):
Sharing a sentence is not in itself a finding about the gene and the disease.
tumor (continued). "Furthermore, pharmacological inhibition of USP10 using Spautin-1 synergizes with cisplatin to enhance anti-tumor efficacy, suggesting a potential therapeutic strategy for overcoming chemoresistance." (PMID 41522354, 2026). "Notably, Spautin-1, a potent USP10 inhibitor, demonstrates synergistic therapeutic activity with cisplatin in diminished tumor growth and metastasis in NPC mice." (PMID 41522354, 2026). "Notably, pharmacological inhibition of USP10 using Spautin-1 synergistically enhanced the anti-tumor efficacy of cisplatin, significantly suppressing tumor growth in preclinical models." (PMID 41522354, 2026). "In this study, we uncovered that USP10 knockdown significantly inhibits tumor growth in NPC." (PMID 41522354, 2026). "Here, our study revealed that knockdown expression of MRPS7 and MRPS23 exhibited an anti-tumor effect and have a synergistic effect with cisplatin, further investigation into the regulatory mechanisms revealed that USP10 acts as a key regulator of MRPS7 and MRPS23 expression." (PMID 41522354, 2026). "Importantly, USP10 protein was obviously correlated with multiple clinical parameters, such as primary tumor site, T classification, clinical stage, lymph node or distant metastasis (all p < 0.05)." (PMID 40605431, 2025). "Previous studies revealed a strong link between USP10 and tumor biology." (PMID 40069750, 2025). "Our study demonstrated that USP10 acted as a tumor promoter and deubiquitinated PLK1 in PDAC." (PMID 40517136, 2025). "Restoring B7‐H4 turnover by inhibiting USP10 could potentially convert a cold tumor immune environment to a more responsive one, thereby increasing SG effectiveness." (PMID 39206932, 2024). "Notably, genes, such as DDX11 (12p11.21), IGLV2-18 (22q11.22), OR8G5 (11q24.2), PARP4 (13q12.12), USP10 (16q24.1), and ZNF208 (19p12), exhibited multiple mutations and demonstrated tumor-driving effects." (PMID 39711964, 2024). "Similarly, 4T1‐hTROP2 cells with USP10 knockdown and subsequent reintroduction of B7‐H4 also showed notable increases in tumor growth and enhanced resistance to SG, confirming the axis's critical role in TNBC progression and response to SG therapy." (PMID 39206932, 2024). "However, in APC-truncated cancer cells USP10 binds to β-catenin, increasing its stability which is critical for maintaining an undifferentiated tumour identity." (PMID 39443725, 2024). "To determine whether alteration of USP10 could directly affect tumor cell proliferation independently of immune system interactions, we conducted experiments using nude mice bearing 4T1‐USP10‐OE or 4T1‐USP10‐KD xenografts." (PMID 39206932, 2024). "Furthermore, our observation reports a direct interaction between USP10 and β-Catenin, confirming that both proteins do regulate tumour-intrinsic processes." (PMID 39443725, 2024). "Moreover, we tested for a genetic interaction between APC truncation and USP10 in a tumour-like setting using the ApcQ8 hyperplasia model." (PMID 39443725, 2024). "Interestingly, ADC treatments seem to trigger a feedback loop that boosts USP10 expression, which, in turn, increases B7‐H4 levels, further compromising the immune system's ability to monitor and attack tumor cells." (PMID 39206932, 2024).
tumor (continued). "Based on the integration of unbiased big data analyses, mass spectrometry and experimental validation including preclinical models, we identified the impact of the USP10/B7‐H4 proteolytic axis in orchestrating tumor immunogenicity and the therapeutic efficacy of ADCs." (PMID 39206932, 2024). "Despite the findings suggesting that USP10 functions as a tumor suppressor, other studies have indicated that USP10 may enhance the migration and invasion of GC cells through RFC2 stabilization." (PMID 39605891, 2024). "Furthermore, we investigated the relationship between USP10 levels and different clinicopathological features of OS and found that higher USP10 expression was correlated with larger tumor size, more metastases and worse TNM stage." (PMID 37184153, 2023). "Therefore, the genetic alterations of USP10 were examined in various tumor samples in the TCGA database." (PMID 35433424, 2022). "In addition, we elucidated the novel role of USP10 in the regulation of tumor immunity in KIRC and HNSC through bioinformatics analysis." (PMID 36248971, 2022). "In addition to USP10 controlling cell proliferation, a study from the Ouchida group revealed that USP10 promotes tumor migration or invasion." (PMID 35627217, 2022). "We next found that USP10 coordinately promotes tumor progression with G3BP1." (PMID 34967276, 2022). "Studies have identified USP10 to be involved in tumor progression in various cancers." (PMID 35433424, 2022). "Unequivocally, enforced expression or knockdown of USP10 could attenuate the tumor-promoting or inhibiting effects induced by overexpression or silencing of circWSB1, respectively." (PMID 35351136, 2022). "We will further discuss the oncogenic and tumor-suppressor roles of USP10 in the following section." (PMID 35627217, 2022). "Numerous studies have reported the diverse roles of USP10 in tumor progression." (PMID 36582601, 2022). "Nevertheless, USP10’s exact role in tumor immunity requires further exploration." (PMID 35433424, 2022). "As such, technologies such as polymer chemistry and selective structural modification may offer strategies to improve both the anti-tumor effects of USP10 inhibitors and their selectivity for tumor cells." (PMID 36248971, 2022). "In addition, USP10’s mRNA expression was downregulated in clinical HCC tissue samples compared with adjacent non-tumor samples." (PMID 35627217, 2022). "Taken together, all these findings suggest that USP10 also functions as a tumor suppressor." (PMID 35627217, 2022). "Our data feed the ongoing debate regarding whether USP10 exerts an oncogenic role or a tumor suppressor role in OC." (PMID 34967276, 2022). "For example, if the gene deubiquitinated by USP10 is an oncogene, it may lead to tumor progression, and if the gene deubiquitinated by USP10 is a tumor suppressor gene, it may lead to tumor suppression." (PMID 36248971, 2022). "Thus, the results of the present study revealed the possible use of USP10 as a cancer biomarker and its function in tumor immunology." (PMID 35433424, 2022). "Collectively, our study provides new insights into the tumor promoting role of USP10." (PMID 36543867, 2022).
tumor (continued). "Interestingly, the normal ovary tissue sample had moderate USP10 staining, while tumor tissue had low staining." (PMID 35433424, 2022). "To test whether reduced USP10 also negatively affected tumor metastasis in vitro, we used transwell assay to evaluate cell migration and invasion levels." (PMID 34967276, 2022). "Consistently, tumor weight was considerably decreased in USP10 knockdown SKOV3 and ES-2 xenografts." (PMID 32382008, 2020). "CAPRIN-1 enhances proliferation, whereas USP10 inhibits tumor progression and invasion." (PMID 32882814, 2020). "Moreover, numerous studies have demonstrated that USP10 inhibited mTOR activation and promoted oncogene-induced senescence to exert a tumor-suppressive effect." (PMID 33178587, 2020). "As for USP10’s tumor type-specific role, we suspect that USP10 behaves similarly to Notch and TGFβ." (PMID 32382008, 2020). "Ablation of USP10 significantly reduced tumor size in all four cell lines tested." (PMID 32382008, 2020). "Moreover, tumor growth inhibition shown as T/C% (treatment/control ratio) in USP10 knockdown xenograft is 45%, while the one in control xenograft is 95%." (PMID 32382008, 2020). "USP10 knockdown in xenografts sharply reduced both tumor volume and tumor weight." (PMID 32382008, 2020). "However, we found that only 50% of patients (9/18) have the reduced expression of USP10 in tumor tissues, implying that additional factors are involved in regulation of USP10 expression in NSCLC." (PMID 27003362, 2016). "Furthermore, EZF stability and activity are finely regulated by post-translational modifications, ubiquitination by enzymes such as USP10, and interactions with oncogenic pathways, indicating that its role in the tumor immune microenvironment is intricately controlled at multiple levels." (PMID 40533866, 2025). "However, the role of USP10 in tumor progression remains controversial." (PMID 38689092, 2024). "Moreover, co-treatment of cisplatin with the USP10 inhibitor Spautin-1 significantly enhanced its anti-tumor effects, suggesting that targeting this axis could offer a new therapeutic approach for OS." (PMID 39218913, 2024). "Notably, the tumor volume curve indicated that USP10 knockdown significantly inhibited PDAC growth." (PMID 39430239, 2024). "Therefore, the role of USP10 in tumor development needs to be further investigated." (PMID 38689092, 2024). "Therefore, we found that knocking down USP10 expression could mediate anti-tumor effects, which were partially blocked by FOXC1." (PMID 39430239, 2024). "Although USP10 may act as a tumour suppressor, its role in different tumours remains controversial." (PMID 36969062, 2023). "Also, USP10 expression is closely connected with the incident of OS metastasis and tumor size." (PMID 37184153, 2023).
tumor (continued). "Furthermore, USP10 could deubiquitinate sirtuin 6 (SIRT6) to antagonize transcriptional activation of c-Myc oncogenes to inhibit tumor formation." (PMID 35433424, 2022). "Thus, USP10 may act as a tumor suppressor in OC, however, more research is needed to elucidate its precise role." (PMID 36248971, 2022). "We performed a literature search to evaluate the structure and biological activity of USP10, summarize its role in tumorigenesis and tumor progression, and discuss how USP10 may act as a tumor suppressor or a tumor-promoting gene depending on its mechanism of action." (PMID 36248971, 2022). "However, it remains unclear how USP10 regulates immunity and whether USP10-mediated deubiquitination may affect tumor response to immunotherapy." (PMID 36248971, 2022). "Also, given the significant transforming role SYK in other tumours, targeting USP10 may have broader applications in cancer." (PMID 32015510, 2020). "Thus, USP10 can act as both tumor suppressor and oncogene, depending on the type of cancer." (PMID 33277473, 2020). "Ubiquitin-specific peptidase 10 (USP10), a DUB, plays a complex role in tumor progression and can act as both a tumor promoter and suppressor in different cancers." (PMID 40517136, 2025). "USP10 and USP13 can mediate the deubiquitination of the autophagy-related protein Beclin1, stabilizing Beclin1 levels and exerting a tumor-suppressive effect." (PMID 40083330, 2025). "The exogenous and endogenous circTP53 interaction with USP10 was further confirmed through RIP assay in both the same HNSCC cell lines and patient's adjacent and tumor tissues." (PMID 40464594, 2025). "Overall, our study demonstrates that USP10 stabilises β-Catenin, promotes WNT-signalling and cancer stemness, essential to tumour onset and development in an APCΔAAR-truncation dependent manner." (PMID 39443725, 2024). "We demonstrated the cellular protein levels of B7‐H4 are dictated by the proteolytic machineries USP10 and AMFR, whose deregulation dampens tumor immune activity and cytotoxic effectiveness of ADCs." (PMID 39206932, 2024). "Our findings reveal, therefore, a role for USP10 in CRC cell identity, stemness, and tumorigenic growth by stabilising β-Catenin, leading to aberrant WNT signalling and degradation resistant tumours." (PMID 39443725, 2024). "On the other hand, USP10 overexpression promoted YAP1 expression, improved EMT, and simultaneously increased distant tumor metastasis." (PMID 37184153, 2023). "In parallel there was a dramatic elevation in USP10 and RUNX1 protein levels in recurrent MES GBM tissues, in comparison to primary PN tumor ones." (PMID 36949071, 2023). "LncSOX21-AS1 encourages tumor stemness and EMT by attracting USP10, thereby promoting the deubiquitination of SRY-box transcription factor 21 (SOX21)." (PMID 38174069, 2023). "The results of H&E staining indicated that the xenografts carrying USP10 shRNA LN229 and GBM2 cells displayed restricted tumor growth, whereas this effect was reversed by overexpression of RUNX1." (PMID 36949071, 2023). "To probe into the functional roles of USP10, USP14, OTUB1, and STAMBP in HSC2 cells, we conducted assays to measure cell proliferation, in vitro invasion, and in vivo tumor growth." (PMID 37986681, 2023). "Our study showed that USP10, USP14, USP18, USP32, USP33, and USP39 (termed as six-USPs) expressions were significantly elevated in tumor tissues." (PMID 36582601, 2022).
tumor (continued). "The results, which were adjusted for tumor purity, showed that in PAAD and LIHC, the expression level of USP10 correlated significantly with most immune markers for the various immune cells." (PMID 35433424, 2022). "Therefore, paradoxically, USP10 might also function as a tumor suppressor in HCC." (PMID 36248971, 2022). "USP10-mediated deubiquitination stabilized NLRP7 protein expression and induced polarization of tumor-promoting M2-like macrophages through NF-κB pathway-mediated monocyte chemoattractant protein-1 (MCP-1) secretion." (PMID 36248971, 2022). "To investigate the action of USP10 on ESCC cells proliferation, we performed the colony formation, EdU incorporation and tumor xenograft formation assays." (PMID 36163081, 2022). "Ubiquitin-specific peptidase 10 (USP10) was reported to interact with YAP1 and TAZ to suppress their ubiquitination, resulting in accelerated HCC tumor growth." (PMID 36289774, 2022). "The expression levels of CCL2 in peripheral blood and tumor tissues were significantly lower in sh-NLRP7-treated and sh-USP10-treated mice than in control mice and higher in NLRP7-treated mice with USP10 knockdown." (PMID 33838681, 2021). "NLRP7 protein levels were increased by USP10-mediated deubiquitination in CRC cells, which induced the polarization of pro-tumor M2-like macrophages via NF-κB pathway-mediated CCL2 secretion." (PMID 33838681, 2021). "In animal studies, macrophages were reduced in the TME of xenograft tumor tissues in NLRP7 and USP10 knockdown groups and were increased in the NLRP7 overexpressing group." (PMID 33838681, 2021). "USP10 and USP13 are critical in the development of several cancers because they regulate some key tumor promoters or suppressors." (PMID 30975171, 2019). "Similar to Beclin 1 knockdown, we found that suppression of the ubiquitin-specific peptidase, USP10, or a small molecule inhibitor of the deubiquitinases USP10 and USP13, i.e., spautin-1, can increase radiation-induced DSBs and promote tumor cell death." (PMID 24956373, 2014). "In seven cases (UCHL1, USP9X, USP11, USP10, USP22, COPS5 and COPS6), dysregulation was observed in more than one tumor type." (PMID 21283576, 2011). "Taken together, these results suggest USP10 inhibition may sensitize PI3Ki-resistant tumors to PI3K pathway downregulation and tumor regression." (PMID 40991650, 2025). "In line with our RNA-Seq analysis, USP10 expression correlated with upregulation of PI3K gene expression signatures in tumor tissue only, with little to no USP10 expression being observed in the associated tumor stroma." (PMID 40991650, 2025). "When USP10 knockdown was combined with GEM treatment, tumor growth was further suppressed." (PMID 40517136, 2025). "Overall, our findings indicate that USP10-ATMIN-LCK axis regulates NPC docetaxel sensitivity and promotes tumor growth, which may provide a potential therapeutic target for the management of NPC." (PMID 38321024, 2024). "In cancer, the function of USP10 as a tumour suppressor or proto-oncogene, is still not fully solved." (PMID 39443725, 2024).